CTSD (cathepsin D)
Diseases named in the same sentence as CTSD in open-access papers (continued):
Sharing a sentence is not in itself a finding about the gene and the disease.
ovarian carcinoma (17 papers, 1998 to 2024). A malignant neoplasm originating from the surface ovarian epithelium. "In ovarian cancer, abundant lysosomes and activated cathepsin D found in cisplatin-resistant SKOV3/DDP cells are required for the maintenance of autophagic flux, partially involved in the promotion of cisplatin resistance." (PMID 38247807, 2024). "Securin and cathepsin D expression were assessed by immunohistochemistry in an independent set of 20 prostate, 47 breast, 20 lung, and 11 ovarian cancer samples." (PMID 17183660, 2006). "The aim of this study was to analyse the clinical significance of Cathepsin D (Cath D) content as determined by an immunoradiometric assay in a series of primary untreated ovarian cancers from 162 patients." (PMID 9862578, 1998). "In an analysis of 1200 cancer-related genes in ER + ovarian cancer cell lines, PEO1, TNFDF1, FOSL1, TRAP1, cathepsin D, and TFAP4 were found to be upregulated in response to insult with estrogens." (PMID 35873467, 2022). "PR, cathepsin D, and C-FOS have also been detected in ER + ovarian cancers while C-MYC, SDF-1, and TGFα have been found to be exclusively expressed in ovarian tumors." (PMID 35873467, 2022). "Differentiation between benign and malignant ovarian tumors was based on autoantibodies against nuclophosmin, GRP78, cathepsin D, and SSX." (PMID 29291021, 2017). "We next evaluated the potential of 25HC to regulate the expression of well known ERα target genes, such as pS2, PR, Cathepsin D, Cyclin A and Cyclin D1 in MCF7 breast and BG-1 ovarian cancer cells." (PMID 21304949, 2011). "Eight immune factors (IFT57, MAL, ANXA4, SCRN1, LTBR, KIFAP3, HSPA5, and LTN1) were positively correlated with poor prognosis of ovarian cancer, whereas six immune factors (PSMB9, FOXJ1, CTSH, MIF, CTSD, and PSMB8) were negatively correlated with poor prognosis of ovarian cancer." (PMID 34109184, 2021). "In this study, we discovered that QC significantly upregulates cathepsin L (CTSL) but not CTSB and CTSD, implicating the specific role of CTSL in promoting QC-induced autophagic flux in ovarian cancer." (PMID 33919392, 2021).
atherosclerosis (15 papers, 2017 to 2025). A disease characterized by the build-up of fatty material and calcium deposition in the arterial wall resulting in partial or complete occlusion of the arterial lumen. "Taken together, these results suggest that cathepsin D not only represents a cancer biomarker but also implicated in the pathogenesis of tau degradation and atherosclerosis." (PMID 29375176, 2017). "The Cathepsins family, including cathepsin B and cathepsin D, potentially affects the entire processes involved in atherosclerosis." (PMID 33964876, 2021). "As an indicator of autophagic activity, CTSB and CTSD were involved in the regulation of cell death and survival in the development of atherosclerosis." (PMID 33964876, 2021). "Proteomic analysis reveals proteins associated with the formation of atherosclerosis, including mimecan (osteoglycin), Ras-1 suppressor protein (RSUP-1) and cathepsin D, which are simultaneously identified as biomarkers of cancer tumours." (PMID 34948066, 2021). "Previous studies have suggested that cathepsin D plays an important role in cholesterol trafficking and atherosclerosis." (PMID 29375176, 2017). "On the other hand, multiple lines of evidence have demonstrated that cathepsin D participates in the pathogenesis of atherosclerosis." (PMID 29375176, 2017). "KTRI for hawthorns in the PVAT microenvironment of atherosclerosis were CTSD, PPARG, and HMOX1." (PMID 40824771, 2025). "KTRI for hawthorn in the PVAT microenvironment of atherosclerosis were CTSD, PPARG, and Hmox1." (PMID 40824771, 2025). "In addition, Cathepsin-D is not only a promoter of atherosclerosis, but also an enzyme involved in the instability of the atheroma plaque by generating apoptosis of macrophages and foam cells." (PMID 36362423, 2022). "The dynamic balance between high expression of cathepsin D and cathepsin D inhibitors is disrupted, leading to the transformation of macrophages into foam cells, which are prone to apoptosis mediated by cathepsin D, leading to atherosclerosis." (PMID 36011406, 2022). "CTSD, a major lysosomal protease, is increasingly known for its involvement in inflammatory response, and has been proposed as biomarkers of several inflammatory diseases, such as non-alcoholic steatohepatitis, atherosclerosis and coronary heart disease." (PMID 33563285, 2021). "The changes in the expression level of CTSD would further lead to the destruction of the dynamic balance of extracellular matrix synthesis and degradation, helping macrophages to become foam cells, mediate the apoptosis of foam cells, and ultimately promote the occurrence of atherosclerosis." (PMID 40824771, 2025). "Thus, complementary to traditional therapies, medication with a role in lowering the level of Cathepsin-D, could improve the prognosis of patients in both primary and secondary prevention of atherosclerosis." (PMID 36362423, 2022). "In conclusion, this study found that the important direct targets of hawthorn in atherosclerosis included IL1B, CTSD, HMOX1, and PPARG." (PMID 40824771, 2025). "Despite the opposite conclusion, to be sure, CTSB/CTSD played an important role in the development of SCD and involved the severity of atherosclerosis." (PMID 33964876, 2021). "Then, six hub genes (COL1A1, IBSP, CTSD, RAC2, MAF, and THBS1) were obtained through the integration of multisource databases and they were all significantly upregulated in both the osteoporosis and atherosclerosis group compared with the control group." (PMID 35937806, 2022).
colorectal cancer (15 papers, 2012 to 2025). A primary or metastatic malignant neoplasm that affects the colon or rectum. "The concentration of cathepsin D in chronic ulcerative colitis and familial adenomatous polyposis, which is known to associate with the increase risk of colorectal carcinoma and colon carcinoma, was higher than that of normal colon." (PMID 22919486, 2012). "On the TCGA colorectal cancer dataset, RTCpredictor re-identified five out of eleven known read-throughs (CTSD-IFITM10, GCSH-C16orf46, METTL21B-TSFM, SLC2A11-MIF and TRIM2-MND1)." (PMID 38796690, 2024). "Cathepsin-D activity increases uncontrolled in cancer cells and its high extracellular level has been detected also in colorectal cancer." (PMID 37108361, 2023). "A high level of mRNA expression and protein level of Cathepsin-D were observed in colorectal cancer." (PMID 37108361, 2023). "The elevation of CTSB and CTSD concentrations was shown in the sera of patients with some tumor types, including colorectal cancer, and bladder cancer." (PMID 26995190, 2016). "In one of the recent reports, CTSD was found to be highly expressed in cells from the primary tumor tissue in late stage colorectal cancer and showed significant correlation with subsequent distant metastasis and shorter cancer-specific survival." (PMID 26203049, 2015). "Cathepsin D expression in the main tumor body warrants further consideration as a potential biomarker of prognosis in colorectal cancer." (PMID 22919486, 2012). "Cathepsin D might represent a therapeutic target for curing invasive colorectal cancer, given that it is only detected in invasive areas of the tumor." (PMID 34198733, 2021). "They suggested the essential role of cathepsin D in colorectal cancer progression." (PMID 34198733, 2021). "For example, enhanced cathepsin D expression was observed in the invasive front of Oesophageal Squamous Cell Carcinoma tumors (in comparison to the cancer nests) and is a common feature in gastric carcinoma, oral carcinoma, and colorectal carcinoma." (PMID 33266503, 2020). "The extent of N‐glycosylation at this specific residue influences CTSD's enzymatic capacity to hydrolyze acyl‐CoA dehydrogenase, medium chain (ACADM), thereby facilitating the liver metastasis of colorectal cancer." (PMID 39716927, 2025). "In our present IHC microarray study, neither strong expression of cathepsin D in macrophages nor the abundance of macrophages themselves at the IF of colorectal cancer tissue correlated particularly with other important clinico-pathological parameters, survival or metastasis." (PMID 22919486, 2012).
diabetes (15 papers, 2016 to 2025). "Cathepsin D has also been linked to ceramide-induced pro-inflammatory and pro-apoptotic pathways, connecting ceramide involvement in diseases such as diabetes mellitus." (PMID 39769156, 2024). "For example, cathepsin D is involved in the development of disorders associated with diabetes or its involvement in redox response suggesting the potential use of this protease in anti-photoaging therapies." (PMID 34198733, 2021). "Twenty-six proteins were positively associated with diabetes, including cathepsin D, retinal dehydrogenase 1, α-l-iduronidase, hydroxyacid oxidase 1 and galectin-4 (top five findings)." (PMID 31446444, 2019). "Despite the important roles of cathepsin D in many physiological and pathological conditions, whether its circulating levels associated with diabetes and clinical variable remain to be established." (PMID 29375176, 2017). "In conclusion, we provide the first evidence that increased level of cathepsin D serves as a novel determinant of type 2 diabetes and measurement of circulating levels may be helpful for assessment of diabetes risk." (PMID 29375176, 2017). "HIIT, vitamin D3 injection, and their combined treatment significantly decreased the levels of Beclin-1, Fyco-1, and cathepsin D and increased the levels of mTOR and pmTOR compared to the diabetes control group (p < 0.001)." (PMID 40144137, 2025). "Exercise training can regulate the expression and activity of CTSD and thus improve autophagic flux and cell homeostasis, which can improve metabolic control and reduce inflammation in diabetics." (PMID 40144137, 2025). "Increased circulating CTSD levels were found in patients with coronary heart disease and diabetes mellitus, which correlated with the severity of heart failure." (PMID 36742461, 2023). "The data concerning the influence of excessive cathepsin D activity outside the lysosomes on the severity of diabetes are relatively scarce." (PMID 34198733, 2021). "The top 5 proteins we identified (GDF15, GAL4, IL1RT1, CTSD and SELE) are robustly associated with diabetes in a variety of studies, consistent with our findings." (PMID 34372849, 2021). "Monocytes with highly expressed CTSD were found in patients with T2D, and genetic ablation of CTSD in the monocytes could exhibit protective effects against the diabetes-induced cognitive impairment in mice." (PMID 40135071, 2025). "The present results of mRFP-GFP-LC3 fluorescence probe and AO staining indicated that HGF impaired the autophagic flux in CFs, which was also supported by the increased expression of LC3-II, P62, and active-cathepsin D. These results provide novel insights for the diabetes mellitus induced MF." (PMID 35165268, 2022). "When further adjusting for established risk factors (model 2), all 7 proteins remained significantly associated with incident diabetes; 5 proteins (CD163, Gal-4, CTSD, PAI and FABP4) with an increased risk of diabetes and 2 proteins (PON3 and IGFBP-2) with a decreased risk for incident diabetes:." (PMID 30670722, 2019). "We demonstrate for the first time that diabetes leads to destabilization of lysosomes as well as alterations in the protein expression, activity, and/or trafficking of two lysosomal enzymes, hexosaminidase A and cathepsin D, in the hippocampus of db/db mice." (PMID 25976368, 2016).
melanoma (15 papers, 2011 to 2025). A malignant, usually aggressive tumor composed of atypical, neoplastic melanocytes. "Cathepsins cover many different types of proteases, but the cysteine based Cathepsin B, and L and aspartic based Cathepsin D, are most associated with an increased in vitro proliferation and progression of melanoma." (PMID 36005056, 2022). "Subsequent investigation of lysosomal protease processing revealed that CEP treatment impaired the proteolytic maturation of both cathepsin B and cathepsin D in a concentration- and duration-dependent manner across melanoma cell lines." (PMID 40862710, 2025). "GILT expression upregulated cathepsin D enzymatic activity in two distinct melanoma cell lines, pointing again to a role for GILT in altering the spectrum of functional peptides for class II presentation and CD4+ T cell recognition." (PMID 35162988, 2022). "An increase in cathepsin D expression and activity would aid melanoma cells in enhanced Ag processing and the presentation of class II–peptide complexes to CD4+ T cells." (PMID 35162988, 2022). "Cathepsin B (CTSB) and cathepsin D (CTSD) are key mediators of lysosomal-mediated cell death and cathepsin inhibitors reduce human melanoma growth and lung metastasis." (PMID 36430634, 2022). "Immunohistochemical studies have shown that CTSD is markedly expressed in melanoma cell lines and tissue biopsies from primary and metastatic melanoma, and these correlate with poor outcome." (PMID 22084687, 2011). "We identified 5 melanoma-associated antigens using this microarray coupled to mass spectrometry; GRP75, GRP94, ASAH1, CTSD and LDHB." (PMID 22084687, 2011). "Two proteins, nuclophosmin/B23 and hepatoma-derived growth factor (HDGF), were strongly upregulated in melanoma, while cathepsin D was downregulated in melanoma cell lines." (PMID 22084682, 2011). "Interestingly, it has been shown that expression levels of CTSD in peripheral blood are predictive of survival in patients with melanoma treated with tremelimumab." (PMID 26203049, 2015). "Quantitative analysis of transcripts for cathepsin genes CTSA, CTSB, and CTSD corroborated that ectopic expression of LAMP-2C in melanoma cells did not increase the expression of these lysosomal enzyme mRNAs." (PMID 30211163, 2018).
prostate carcinoma (13 papers, 2014 to 2025). A carcinoma that arises from epithelial cells of the prostate gland. "Recently two novel cancer-related glycoproteins, thrombospondin 1 (THBS1) and cathepsin D (CTSD) were proposed as blood-based biomarkers that outperformed PSA in distinguishing benign disease from prostate cancer in men with enlarged prostate gland." (PMID 33924671, 2021). "The exosomal (CD9- CD81-SCARB2) (average enrichment 2.40) and lysosomal (CTSD- LAMP2- CTSZ- SPNS1- PSAP) (average enrichment 4.15) proteins were also enriched in exosomes from prostate cancer patients." (PMID 26196085, 2015). "Olfactomedin 4 suppressed prostate cancer cell growth and metastasis via interaction with cathepsin D and stromal cell derived factor-1-1." (PMID 24495253, 2014). "ROS-induced oxidative stress triggers the release of lysosomal protease cathepsin D into the cytosol which leads to induction of cytochrome c released from mitochondria and activation of apoptotic cascades in prostate cancer cells." (PMID 25255125, 2014). "Namely, initial papers on the potential of THBS1 and CTSD signature in prostate cancer were published in 2017, 2019, and 2020 and were based on the earlier analyses of the serum proteome in metastatic castration-resistant prostate cancer patients and the PTEN conditional knockout mouse model." (PMID 38255186, 2023). "Cathepsin D is also responsible for angiostatin generation in human prostate carcinoma cells." (PMID 30943905, 2019). "The increased levels of several endosomal/lysosomal peptidases (e.g. cathepsin D, carboxypeptidase Q, probable serine carboxypeptidase CPVL, napsin A) in prostate cancer patients urinary exosomes could be related to cancer progression." (PMID 26196085, 2015).
myocardial infarction (12 papers, 2017 to 2025). Gross necrosis of the myocardium, as a result of interruption of the blood supply to the area, as in coronary thrombosis. "High serum levels of cathepsin D have been shown to associate with new-onset HF following ST segment elevation acute myocardial infarction." (PMID 35216460, 2022). "Recently, high circulatory levels of cathepsin D were shown to be inversely associated with deterioration in cardiac function in patients with acute myocardial infarction." (PMID 29375176, 2017). "CTSD exerts a critical role in the lysosomal degradation of autophagosomes involved in immune response, apoptosis, cancer development, and myocardial infarction 33-36." (PMID 33391533, 2021). "Cardiac autophagy activity was increased after myocardial infarction, if up-regulation of CTSD was prevented during myocardial infarction exacerbates poor cardiac remodeling and dysfunction in mice." (PMID 33964876, 2021). "Oxidative stress results in cytosolic release of lysosomal CTSD, and some clinical studies have reported that circulating CTSD levels are elevated after myocardial infarction until 6 months later." (PMID 32176724, 2020). "In contrast, cardiac CTS levels in heart failure (HF) display phase-dependent changes; CTSD is upregulated in the subacute phase after myocardial infarction and is downregulated in the chronic phase and in the final stage of dilated cardiomyopathy." (PMID 32176724, 2020). "Of importance is CTSD, which is a ubiquitous lysosomal aspartyl protease that was shown to provide an alternative angiotensin production pathway after myocardial infarction, and hence falsely increase clinical plasma renin activity determinations." (PMID 30934934, 2019). "Clinical follow-up analyses showed that serum cathepsin D level in acute myocardial infarction patients was inversely related to cardiac dysfunction." (PMID 29375176, 2017). "Cathepsin D, in particular, is critical for maintaining neuronal survival under ischemic stress and oxygen-glucose deprivation, and its protective role extends to other ischemic conditions, as myocardial infarction." (PMID 41342963, 2025). "Similarly to our study, serum levels of cathepsin D were down-regulated in human with heart failure and myocardial infarction." (PMID 33256720, 2020). "Therefore, the elevation of circulating CTSD after myocardial infarction potentially contributes to angiotensin formation and an increase in blood pressure." (PMID 32176724, 2020). "However, the functional role of CTSD in diabetic cardiomyopathy remains largely unknown, despite a previous study suggesting a protective role for CTSD in myocardial infarction." (PMID 36742461, 2023). "Moreover, CTSD heterozygous mice (CTSD+/-), which do not present with cardiac dysfunction under normal conditions, display impaired autophagic flux and exacerbated cardiac function after myocardial infarction." (PMID 32176724, 2020).